IL17A (interleukin 17A)
Diseases named in the same sentence as IL17A in open-access papers (continued):
Sharing a sentence is not in itself a finding about the gene and the disease.
uveitis (continued). "In this regard, our finding that treatment with Gal-8 during the course of uveitis markedly decreases the soluble levels of both the TH1 cytokine, IFNγ, as well as the TH17 cytokine, IL-17A, in the retina is of interest." (PMID 26126176, 2015). "While IL-17A inhibitors are not yet approved for uveitis, available data and our observation suggest a potential role in selected cases." (PMID 41107632, 2025). "Further studies are warranted to clarify the long-term safety and efficacy of IL-17A blockade in non-infectious uveitis and drug-induced sarcoidosis-like reactions." (PMID 41107632, 2025). "Although later phase III trials reported mixed results and secukinumab has not been approved for uveitis, these findings support the biological plausibility of IL-17A blockade in selected cases." (PMID 41107632, 2025). "Secukinumab, a human monoclonal antibody inhibiting interleukin 17A, is also being investigated as a potential treatment for noninfectious uveitis." (PMID 36451402, 2022). "They found higher levels of IL-1β, IL-4, IL-17A, IL-17F, IL-21, IL-22, IL-31, IFN-γ, sCD40L, and TNF-α, with a significant difference for IL-17F, in BD-recurrent uveitis patients respect to the BD-remitted uveitis group, before drug infusion." (PMID 31134098, 2019). "Similar to the result of percent detectable, the vitreous levels of IFN-γ and sCD40L were significantly higher in uveitis group than in PDR group, whereas those of IL-4, IL-17A, IL-22, IL-31, and TNFα were significantly higher in PDR group compared with uveitis group." (PMID 26352837, 2015). "Former therapeutic antibodies that have only targeted IL-17A were not efficient in treating uveitis, since blocking IL-17A might have been compensated by IL-17F." (PMID 41142785, 2025). "This inconsistency may be due to the different in the experimental setup because IL-17A stimulation is not enough to represent the proinflammatory environment in uveitis for the stimulation of ARPE-19." (PMID 36233291, 2022). "Secukinumab, a human monoclonal antibody inhibiting IL-17A, has been approved for the treatment of psoriasis, psoriatic arthritis and ankylosing spondylitis and it is also being investigated as a potential treatment for noninfectious uveitis." (PMID 36451402, 2022). "Similarly IL-17A expression was also higher in IOTB (2.14 ± 0.29) as compared to non-uveitis control (1.39 ± 0.13, p = 0.046), non-uveitis TB (0.92 ± 0.11, p = 0.002) and apparently higher than in non-TB uveitis group (1.39 ± 0.23, p = 0.07)." (PMID 30218032, 2018). "However, clinical trials targeting IL-17A in uveitis have not been successful, which might be because the IL-17A-targeted drug improved EAU by inducing IL-24 in vivo, but silencing IL-24 in Th17 cells enhanced the disease." (PMID 34795583, 2021). "Therefore, our current study could shed light on the partial or lack of response to a human antibody to IL-17A (secukinumab) treatment in patients with noninfectious uveitis in a few clinical trials." (PMID 32801998, 2020). "In our current study, we performed ELISA to assess the protein levels of IL-10, IL-6, IL-17A, and TNF-α in the serum of non-infectious uveitis patients." (PMID 40433375, 2025). "The levels of EGF, fractalkine, IL1-β, IL-17A, IL-1RA, IL-2, IL-23, IL-8, IP-10, TNF-α and IL-6 in patients with uveitis in their active phase were independent of their counterpart levels in plasma, the difference being statistically significant (p < 0.05)." (PMID 36498608, 2022).
ulcerative colitis (147 papers, 2010 to 2026). An inflammatory bowel disease involving the mucosal surface of the large intestine and rectum. "The most noticeable finding was the linkage of IL23R and IL17A gene region to ulcerative colitis risk due to the gene-gene interaction." (PMID 22984500, 2012). "This study examined the association of IL23R and IL17A gene SNPs with ulcerative colitis susceptibility in a population in China." (PMID 22984500, 2012). "To explore CRISPR-Select modeling of a noncancer disease, we tested loss-of-function variants in NFKBIZ in the IL-17A signaling pathway, which have been identified in ulcerative colitis colon epithelium and shown to confer survival advantage to colon epithelial organoids." (PMID 36471068, 2022). "We demonstrated that IL-17A may be associated with ulcerative colitis activity which accords with other research." (PMID 32724117, 2020). "A study revealed that IL-17A/-197A allele was significantly associated with chronic relapsing phenotype of ulcerative colitis and the -197A/A homozygote was more frequent in steroid dependent cases, while the IL-17F/7488 T allele was associated with the chronic continuous phenotype." (PMID 28101335, 2017). "However, the influence on the pathophysiological features of ulcerative colitis is partially different among IL-17A and IL-17F polymorphisms." (PMID 28101335, 2017). "For example, obefazimod (ABX464), a small molecule that modulates the splicing of lncRNA 0599-205 to enhance miR-124 expression, has shown efficacy in late-phase clinical trials for ulcerative colitis, leading to suppression of IL-6 and IL-17A pathways." (PMID 40981386, 2025). "Jak3 knockout mouse model showing Il-2, Il-4, Il-7, Il-9, and Il-15 conduction defects, elevated levels of Il-6 and Il-17a and severe immunodeficiency, defects in barrier function lead to Ulcerative colitis (UC)." (PMID 33777833, 2021). "We found that serum IL-17A was significantly increased in patients with active phase of ulcerative colitis compared to those in ulcerative colitis remission (p = 0.04)." (PMID 32724117, 2020). "In our study in ulcerative colitis children positive relationship between IL-17A with PUCAI and stool calprotectin showed a tendency toward significance." (PMID 32724117, 2020). "Detailed analysis revealed that in our study group only in patients with ulcerative colitis IL-17A was higher than in controls." (PMID 32724117, 2020). "IL-17A was significantly increased in patients with active phase of ulcerative colitis (median: 14.58 pg/ml; range: 0.65–200.54 pg/ml) compared to those in ulcerative colitis remission (median: 8.13 pg/ml; range: 1.61–58.56 pg/ml) (p = 0.04)." (PMID 32724117, 2020). "IL-17A–producing IL-7Rα+ innate lymphoid cells are potent promoters of intestinal inflammation in Tbx21−/−Rag2−/− ulcerative colitis mice." (PMID 27424033, 2016). "A predominance of ILC3 secreting IL-17A accompanied by few IFN-γ-expressing cells was also described in the Tbx21-/-Rag2-/- ulcerative colitis (TRUC mice) disease model." (PMID 25853847, 2015). "The ability of IL-17A to protect against development of autoimmune uveitis and ulcerative colitis has been demonstrated; however, this contrasts with the reported disease-promoting role of Th17 cells in MS, and will need further clarification." (PMID 23638056, 2013). "A novel association with ulcerative colitis susceptibility occurred in haplotypes of IL23R (Block1 H3 P = 0.02; Block2 H2 P = 0.019; Block3 H4 P = 0.029) and IL17A (H4 P = 0.034)." (PMID 22984500, 2012). "Recently, we have reported that the IL-17A gene (IL17A) polymorphism (rs2275913 G > A) and IL-17 F gene (IL17F) polymorphism (rs763780 T > C) are closely associated with the susceptibility to gastric carcinogenesis, as well as ulcerative colitis." (PMID 22827846, 2012). "Here, we show that interleukin-17A (IL-17A)-producing IL-7Rα+ innate lymphoid cells (ILCs) were potent promoters of disease in Tbx21−/−Rag2−/− ulcerative colitis (TRUC) mice." (PMID 23063332, 2012).
ulcerative colitis (continued). "This study aimed to evaluate the relationship between interleukin 17 (IL-17 A) cytokine, which plays a role in the pathogenesis of ulcerative colitis, and the inflammation-controlled a disintegrin and metalloproteinase with thrombospondin motifs (ADAMTS)-1, -4, and − 5 protein members." (PMID 37798683, 2023). "Andrographolide is able to lower the expression levels of IFN-γ, IL-23, and IL-17A in the peripheral blood mononuclear cells (PBMCs) of patients with ulcerative colitis, increase the expression of IL-4, inhibit the Th1/Th17 immune response and promote the Th2 response." (PMID 36238575, 2022). "Interestingly, in the setting of human ulcerative colitis, expression levels of Hedgehog components positively correlated with the expression levels of key Th17 markers such as IL17A and CCR6." (PMID 35835905, 2022). "Some clinical and pre-clinical studies also demonstrated that ulcerative colitis could lead to a significant increase in serum inflammatory factors, such as IL-17A, IL-6 and CRP." (PMID 35267960, 2022). "Also, T lymphocytes and peripheral blood mononuclear cells responded to ERS by activating the IRE1/XBP1 signaling pathway, promoting secretions of IFN-γ, IL-17A, and IL-2 in a study about ulcerative colitis." (PMID 33933165, 2021). "Moreover, in a group of patients with ulcerative colitis relationship between IL-17A and clinical activity index (PUCAI) and calprotectin nearly reached a statistically significant level." (PMID 32724117, 2020). "Moreover, we presented that IL-17A was significantly increased in patients with active ulcerative colitis compared to those in ulcerative colitis remission." (PMID 32724117, 2020). "Our findings may suggest that IL-17A may be a marker of ulcerative colitis clinical activity in children." (PMID 32724117, 2020). "Similarly, recent studies on ulcerative colitis have suggested a crucial role of the Th17 cell pathway in triggering the inflammatory response in these patients, and increased levels of IL-23 and IL-17A have been identified in the cells of colonic mucosa on immunohistochemical analysis." (PMID 40309466, 2025). "To investigate whether the differences in response to IL-17A between the ECO could be linked to a specific mutational signature, we examined somatic mutations based on the previously published work on ulcerative colitis and the IL-17 signaling pathway in the PSC ECO." (PMID 38829197, 2024). "Similarly, IL-17A levels in ulcerative colitis mouse models were also significantly increased." (PMID 34407839, 2021). "T cell/ILC-associated genes most highly expressed in LPLs from infected Maffl/flCd4Cre mice, including IL17A and IL17F, were highly expressed in human IBD, again to a higher extent in ulcerative colitis." (PMID 38609547, 2024). "In the colon of patients with ulcerative colitis (IBD), a positive correlation exists between the mRNA levels of IL-17A and IL-17C." (PMID 34103614, 2021). "Several issues still have to be addressed concerning the role of ILC3 in inflammatory settings: an increase in IL-17A-producing ILC3s was reported in IBD, correlating with mucosal leakage in ulcerative colitis patients." (PMID 35003122, 2021). "A total of 270 ulcerative colitis and 268 healthy controls were recruited for the analyses of 23 SNPs in the IL23R and IL17A regions." (PMID 22984500, 2012). "In contrast, FMT from healthy donors reduced IL-17A levels in ulcerative colitis models, suggesting a protective effect in non-neoplastic inflammation." (PMID 41614846, 2025). "Moreover, it inhibited TNF-α, IL-1β, IL-12 IL-17A, and interferon-γ (IFN-γ) contents that were elevated due to ulcerative colitis." (PMID 36079895, 2022). "In silico analysis of transcript expression in colonic biopsies showed a 10‐fold increase in IL17A mRNA in samples from people with ulcerative colitis (UC), compared to noninflamed controls (NI) (p = 4.6 × 10−9, one‐way ANOVA with Benjamini‐Hochberg post hoc test; data redrawn from)." (PMID 40827457, 2025).
ulcerative colitis (continued). "Moreover, we found a negative relationship between IL-17A with haemoglobin, haematocrit, and medium cell value in children with ulcerative colitis." (PMID 32724117, 2020). "We found negative correlations between IL-17A and haemoglobin level (p = 0.02; R = − 0.36), haematocrit (p = 0.002; R = − 0.47) and medium cell value (MCV) (p = 0.01; R = − 0.36) in ulcerative colitis." (PMID 32724117, 2020).
atopic dermatitis (145 papers, 2011 to 2026). "The IL-17A polymorphism was investigated in the aspect of the presence of atopic dermatitis in the Polish population." (PMID 30304837, 2018). "Just one work until now investigated the relationship between IL17A polymorphism and IL-17A levels and the authors showed that serum concentration of IL-17A was significantly higher in the presence of allele A (AA and AG genotypes) in a population of Chinese patients with atopic dermatitis." (PMID 25136146, 2014). "In atopic dermatitis pathogenesis, inflammatory cytokines of the Th2, Th17, Th1, and Th22 subclasses, such as IL-4, IL-13, IL-17A, INF-γ, IL-12A, and IL-22, play important roles." (PMID 38672764, 2024). "With the HB0034SA and anti-IL-17A antibody HB0017 that cross-reacts to mouse IL-17A, we compared the anti-inflammatory effect of combination of two mAbs to single mAbs in oxazolone-induced mouse atopic dermatitis model." (PMID 39600699, 2024). "IL-17A-induced IL-33 also promotes type 2 immunity during atopic dermatitis with the IL-17A source being ILC3s12." (PMID 37783278, 2023). "For instance, IFN-ɤ+, IL-4+, or IL-17A+CD4+T cells (Th1, Th2, or Th17) and IL-17A+ɤδT cells, are famous effector T cells (Teff) that increase in atopic dermatitis (AD) skin." (PMID 30060633, 2018). "Skin biopsy specimens from Asian children with atopic dermatitis express significantly higher levels of T helper Th17‐ and Th22‐related cytokines (especially interleukin (IL)‐17A, IL‐19, and IL‐22) and IL‐17/IL‐22 than found in skin biopsy specimens from European American children." (PMID 36705040, 2023). "IL-17A can induce Th2 responses in murine models of atopic dermatitis and Th2 cells making both IL-4 and IL-17 have been seen in human allergic asthma and AD and may correlate with disease activity." (PMID 35265075, 2022). "Of particular interested was IL-17A; this protein was found to be present at higher levels in the asthmatic subjects who suffered additional atopic complications (Asthma_1, Asthma_2, and Asthma_4) and the two control subjects who had self-reported atopic dermatitis (Control_2 and Control_3)." (PMID 31221987, 2019). "Although younger CD4CreTTPf/f mice appeared normal, they did develop atopic dermatitis and had elevated skin TH17 cells and serum levels of IL-17A when they aged past 5–8 months." (PMID 32922402, 2020). "Additionally, DNCB-induced atopic dermatitis mice exhibited significantly increased Th2 (IL-4 and IL-13), Th1 (IFN-γ), and Th17 (IL-17A) cytokine mRNA levels in the cervical lymph nodes." (PMID 38672764, 2024). "In addition, the inflammatory pathogenesis of atopic dermatitis is influenced by Th1 and Th17 cytokines, interferons (IFN)-γ, IL-12A, and IL-17A." (PMID 38541664, 2024).
influenza (142 papers, 2008 to 2025). An acute viral infection of the respiratory tract, occurring in isolated cases, in epidemics, or in pandemics; it is caused by serologically different strains of viruses (influenzaviruses) designated A, B, and C, has a 3-day incubation period, and usually lasts for 3 to 10 days. "A more recent study in mice demonstrated that influenza-induced IL-27 led to a predisposition to secondary pneumococcal pneumonia due to suppression of IL-17A." (PMID 30192848, 2018). "Together, these data suggest that IL-17A deficiency impairs B-1a plasmacytic differentiation during influenza infections." (PMID 26735852, 2016). "Taken together our data showed that in addition to contributing to lung dysfunction, IL-1β played a key role in driving neutrophilic inflammation during influenza-induced exacerbations, an effect that was tightly linked to IL-17A expression." (PMID 24918427, 2014). "Recently, it has been demonstrated that influenza-infected IFNAR-deficient mice were resistant to secondary pneumococcal pneumonia with increased IL-17A production in γδ T cells." (PMID 24408967, 2014). "Based on weight loss, neutrophil ablation of vaccinated mice during influenza infection only partially alleviated symptoms compared to mice treated with anti-IL-17A antibody." (PMID 24465206, 2014). "Targeting IL-17RA signaling or IL-17A could potentially be a therapeutic strategy to mitigate immunopathology associated with sever influenza infections." (PMID 37600066, 2023). "Significant changes in the expression of IL-17A were detected in this study, implying that XEGMG could reduce the lung and intestinal injury caused by influenza in mice by inhibiting the increase of IL-17A levels." (PMID 37036063, 2023). "IL-17A is also associated with exacerbated influenza-associated pathology." (PMID 34504501, 2021). "Consistent with an important role for IL-17A in protection against influenza infection, pdmH1N1-infected IL-17A-deficient (Il17a−/−) mice showed significantly reduced survival rate, increased weight loss and lung injury when compared with infected wild-type mice." (PMID 33772013, 2021). "Since previous studies found that PC-specific natural antibodies were exclusively produced by B-1a cells in naïve mice, these data indicate that IL-17A deficiency might lead to impaired B-1a cell response during influenza infection." (PMID 26735852, 2016). "However, it has remained unclear whether IL-17A deficiency affects B-1 cell response during influenza infection." (PMID 26735852, 2016). "Having observed that IL-17A in γδ T cells was the significant cytokine for enhanced clearance of secondary pneumococcal pneumonia observed in IL-27R-deficient mice, neutralization of IL-17A would dramatically increase sensitivity of influenza-infected IL-27R-deficient mice." (PMID 24408967, 2014). "In mice, lung-derived CCR9+CD4+ T cells migrate to the small intestine via the CCL25/CCR9 axis during influenza infection, contributing to dysbiosis and IL-15-driven Th17 polarization that exacerbates IL-17A-mediated intestinal injury." (PMID 40872830, 2025). "We evaluated serum concentrations of seven cytokines (IL-2, IL-4, IL-6, IL-10, TNFα, IFNγ, and IL-17a) as potential biomarkers for influenza severity in pregnant women." (PMID 40558593, 2025). "There is contradicting evidence on how IL-17A and influenza induces IL-33 production and the downstream effects triggered for tissue repair and remodeling." (PMID 36061377, 2022). "It was proposed that IL-17C would be able to boost IL-17A production to reinforce innate host barrier during influenza infection for example." (PMID 35479098, 2022). "While the links between IL-17A and IL-33 pathways are unclear during influenza infection, they play an important role in type-2 immunity and mediating infection responses in the young." (PMID 36061377, 2022).